FOLR1 (folate receptor alpha)
Diseases named in the same sentence as FOLR1 in open-access papers (continued):
Sharing a sentence is not in itself a finding about the gene and the disease.
cancer (continued). "Using a sensitive clinical assay, we measured FOLR1 protein in the sera of men and women without cancer who were enrolled in an ongoing population-based cohort study in Alberta, Canada." (PMID 24810481, 2014). "Folate receptor alpha (FRA) is a cell surface protein whose aberrant expression in malignant cells has resulted in its pursuit as a therapeutic target and marker for diagnosis of cancer." (PMID 22204844, 2011). "More recently, FOLR1 protein was reported in the sera of women without cancer." (PMID 24810481, 2014). "The positive association between serum FOLR1 concentration and female gender independent of age suggests caution against statements to exploit serum FOLR1 for early cancer detection without further investigation into reasons for its presence in sera of women without cancer." (PMID 24810481, 2014). "The antigens folate receptor 1 (FOLR1) and mesothelin (MSLN) are specifically and highly expressed in cancer tissues, with only 11.25% of samples negative for both antigens." (PMID 40092990, 2025). "Twenty coexpressed upregulated genes were identified from the GEO database, and we found FOLR1 (folate receptor 1) and MSLN (mesothelin) were specifically and highly expressed in cancer tissues and only 11.25% of samples were negative for both antigens." (PMID 34803504, 2021).
adenocarcinoma (9 papers, 2012 to 2024). A common cancer characterized by the presence of malignant glandular cells. "In patients with adenocarcinoma that underwent surgical resection, increased folate receptor alpha expression was associated with improved overall survival (Hazard Ratio 0.39, 95% CI 0.18-0.85)." (PMID 22547449, 2012). "Using RNAscope, a novel ISH method, we confirmed the similarities between EOC and fallopian tube, normal and adenocarcinoma using FOLR1, FOLR2, CD68 and CD11b markers." (PMID 25971554, 2015). "Adenocarcinomas also had a higher median pre-decitabine score for folate receptor-alpha (FOLR1) (90 versus 60, P = 0.0146)." (PMID 24401732, 2014). "Similar to fallopian tube normal and adenocarcinoma samples, and in contract to normal ovary, EOC showed abundant expression of FOLR1 mRNA in the epithelial tumor cells whereas FOLR2 expression was restricted to stromal cells." (PMID 25971554, 2015). "The changes in median IHC scores with decitabine were 30 (adenocarcinomas) versus 20 (others) for RhoA (P = 0.63), 30 (adenocarcinomas) versus 12 (others) for RFC1, -5 (adenocarcinomas) versus 0 (others) for FOLR1 (P = 0.89) and 0 (adenocarcinomas) versus 0 (others) for GLUT4 (P = 0.96)." (PMID 24401732, 2014).
benign tumors (5 papers, 2012 to 2021). "In the current study, Folr1 was abundantly expressed in MB compared with the normal and benign tumors." (PMID 28416738, 2017). "FOLR1 was more highly expressed in benign tumors and even higher in malignant disease (P < 0.01)." (PMID 29433550, 2018).
mitochondrial disease (2 papers, 2018 to 2020). "The primary causes of CFD include the presence of folate receptor (FR) autoantibodies, defects of FR encoding gene FOLR1, mitochondrial diseases and congenital abnormalities in folate metabolism." (PMID 33243190, 2020). "In addition, defects of FR encoding gene FOLR1, mitochondrial diseases and congenital abnormalities in folate metabolism could also lead to CFD." (PMID 33243190, 2020).
colon polyps (1 paper, 2025). "Forth, patients with colon polyps were used as the control group; however, this group may not serve as an appropriate healthy control population, as there is no information regarding the effect of colon polyps on serum FOLR1 levels." (PMID 40038575, 2025).
metabolic disease (1 paper, 2023). A congenital disorder (due to inherited enzyme abnormality) or acquired (due to failure of a metabolically important organ) disorder resulting from an abnormal metabolic process. "A few cases of non-mitochondria-related variants were evaluated as probably having mitochondrial disorders, such as variants in MMACHC, MCEE, FOLR1 and G6PC genes, which were grouped as causative genes of metabolic diseases affecting multiple systems." (PMID 36918699, 2023).
FOLR1 also shares sentences with these, for which no sentence is quoted: fallopian tube cancer (6 papers); acute megakaryoblastic leukemia (4); Autoimmunity (4); developmental delay (4); lung squamous cell carcinoma (4); neural tube defect (4); clear cell carcinomas (3); infection (3); mucinous tumors (3); neurodevelopmental disorder (3); anaphylaxis (2); gingivitis (2); hepatocellular carcinoma (2); invasive breast carcinoma (2); malignant mesothelioma (2); neurologic disorders (2); pancreatic adenocarcinoma (2); renal carcinoma (2); uterine carcinosarcoma (2); acute kidney injury (1); adenomyosis (1); allergic disease (1); anemia (1); anencephaly (1); atherosclerosis (1); B-celllymphoma (1); basophil leukaemia (1); benign cystadenomas (1); blood cancers (1); Brain atrophy (1).
A further 64 diseases each share a sentence with FOLR1 in 1 paper.